PCDH15 (protocadherin related 15)
Diseases named in the same sentence as PCDH15 in open-access papers (continued):
Sharing a sentence is not in itself a finding about the gene and the disease.
deafness (continued). "Of them, 9 deafness genes expressed more in the apical turn (Pou4f3, Slc17a8, Tmc1, Crym, Otof, Ush1c, Pcdh15, Slc26a5, and Lhfpl5) and six were internal controls (Gapdh, Actb, Rps17, Rpl30, Atp6, and Ipo8)." (PMID 24676347, 2014). "Bi-allelic mutations in 15 less commonly screened deafness genes were identified in 28 deaf probands, with mutations in MYO15A, GPR98, TMC1, USH2A and PCDH15 being relatively more frequent (≥3 probands each)." (PMID 23767834, 2013). "Functional null alleles in PCDH15 typically cause USH1, whereas missense mutations in conserved motifs or non-frameshift mutations that alter one or more amino acids, retaining some residual protein function, are commonly associated with recessive deafness." (PMID 40486680, 2025). "Our data suggest that mini-PCDH15 proteins can be used for treating deafness in USH1F patients, and could be tested as a therapy to treat blindness." (PMID 37100771, 2023). "Interestingly, deafness mutations in LHFPL5 do not affect the interaction of PCDH15 and LHFPL5 and in our structure do not localize to interaction sites of PCDH15 and LHFPL5, suggesting that LHFPL5 interacts with additional components of the mechanotransduction complex." (PMID 30070639, 2018). "While the Pcdh15–/– model showed marked preservation of balance, the deafness phenotype was not improved by the dual-AAV treatment in these mice." (PMID 39441757, 2024). "Labeling was absent if PCDH15 lacked EC1 and EC2 or if it bore the deafness mutations I108N or R113G43,44." (PMID 37100771, 2023). "In addition, mutations in MYO7A, USH1C, DFNB31, CIB2, CDH23 and PCDH15 were also reported in non-syndromic deafness without retinal degeneration and mutations in USH2A and CLRN1 have been reported in patients with isolated RP or retinal dystrophies and no deafness." (PMID 25211151, 2014).
hearing loss (33 papers, 2012 to 2025). "For example, double heterozygosity for mutations in Cdh23 and Pcdh15, another tip-link component, significantly increases susceptibility to hearing loss." (PMID 40360853, 2025). "When PCDH15 has a point mutation, V507D, associated with non-syndromic hearing loss, unfolding events occur more frequently under tension and refolding events occur less often than in the wild-type protein." (PMID 37905108, 2023). "Similar with PCDH15, the difference of syndromic and nonsyndromic hearing loss induced by mutation of MYO7A was visual disorder." (PMID 29692870, 2018). "Double heterozygous mutations of CDH23 and PCDH15 have been reported to be a digenic cause of hearing loss." (PMID 24164807, 2013). "PCDH15 mutant alleles can cause either USH1F or non-syndromic hearing loss." (PMID 40486680, 2025). "Mutations of PCDH15 gene cause syndromic and nonsyndromic hearing loss." (PMID 27867666, 2016). "We checked whether any variant from either ATP2B2 or PCDH15 can contribute to hearing loss in this family in trans with the p.P240L of CDH23 as a modifier or in a digenic fashion, as previously suggested." (PMID 27792758, 2016). "The results of gene expression analysis of each cochlear turn showed that 4 ADNSHL genes (Pou4f3, Slc17a8, Tmc1, and Crym) and 9 autosomal recessive non syndromic hearing loss genes (Otof, Strc, Ush1c, Pcdh15, Grxcr1, Dfnb59, Slc26a5, Lhfpl5, and Ptprq) were changed 2-fold or more." (PMID 24676347, 2014). "This family includes protocadherin 15 (Pcdh15), with a known function in the tip links of the stereocilia of the inner ear in conjunction with cadherin 23 and has been associated with multiple mutations in both non-syndromic and syndromic hearing loss in humans." (PMID 24942165, 2014). "Variants in MYO7A, USH1C, CDH23, PCDH15, and WHRN are also responsible for non-syndromic hearing loss associated with loci DFNB2 and DFNA11, DFNB18, DFNB12, DFNB23, and DFNB31, respectively." (PMID 38525684, 2024). "In R4 family, a novel nonsense mutation caused by c.2758 C>T (p.R920X) was detected in PCDH15, which is responsible for both Usher syndrome 1F (USH1F) and deafness autosomal recessive type 23 (DFNB23) hearing loss." (PMID 29568747, 2018). "Sanger sequencing revealed that the other subject with hearing loss (subject II:3) also had both heterozygous CDH23 and PCDH15 mutations." (PMID 24164807, 2013). "When PCDH15 exhibits a point mutation, V507D, associated with nonsyndromic hearing loss, unfolding events occur more frequently under tension and refolding events occur less often than for the wild-type protein." (PMID 39298473, 2024). "Mutations of MYO7A, CDH23, USH1C, PCDH15, USH1G, and WHRN can cause non-syndromic recessive hearing impairment, and MYO7A variants are also associated with a non-syndromic dominant form of hearing impairment." (PMID 35353227, 2022). "This gene, a nonclustered protocadherin PCDH15, plays a key role in the formation of sensory hair cells as well as the retina, and variants within this gene are associated with vision and hearing impairment in humans." (PMID 34745336, 2021).
Usher syndrome type 1 (29 papers, 2007 to 2025). "Mutations in PCDH15 have been associated with Usher syndrome type I (Usher I) and non-syndromic hearing loss." (PMID 33737949, 2021). "No mutational hotspots or recurrent mutations have been identified in the PCDH15 gene, with the exception of p.R245X, a founder mutation responsible for about 50%–60% of Usher syndrome type I cases in the Ashkenazi Jewish population." (PMID 22815625, 2012). "The purpose of this work was to perform PCDH15 mutation screening to identify the genetic cause of the disease in a cohort of Spanish patients with Usher syndrome type I and establish phenotype-genotype correlation." (PMID 22815625, 2012). "Mutations in the PCDH15 gene are responsible for Usher syndrome type I (USH1F) and non-syndromic hearing loss (DFNB23)." (PMID 22815625, 2012). "Furthermore, mutations in PCDH15 are related to Usher syndrome type I and to non-syndromic hearing loss; phenotypes that are not keeping with our patient clinical findings." (PMID 29912909, 2018). "Mutations in PCDH15 are responsible for Usher syndrome type I (USH1F) and DFNB23." (PMID 22815625, 2012). "In PCDH15 patients for whom detailed clinical information was obtained, a typical Usher syndrome type I phenotype was observed." (PMID 22815625, 2012). "In the present study, we report the results of sequence analysis of all 38 coding exons of the PCDH15 gene in 15 probands with Usher syndrome type I and four clinically non-classified USH from the Spanish population." (PMID 22815625, 2012).
Usher syndrome type 1F (17 papers, 2007 to 2025). A form of Usher syndrome type IF that can be caused by homozygous or compound heterozygous mutation in the protocadherin-15 gene (PCDH15) on chromosome 10q. "Genetic variants in PCDH15 that prevent protein binding to cadherin 23 cause Usher syndrome type 1F (USH1F), a disease characterized by retinitis pigmentosa, congenital deafness, and vestibular areflexia." (PMID 35637313, 2022).
retinitis pigmentosa (11 papers, 2012 to 2024). Retinitis pigmentosa (RP) is an inherited retinal dystrophy leading to progressive loss of the photoreceptors and retinal pigment epithelium and resulting in blindness usually after several decades. "Mutations in four cadherin, namely CDHR1, CDH23, PCDH15, CDH3, the latter being the dominant RPE cadherin, have been identified as causes of inherited retinal degeneration, including cone-rod dystrophy, macular dystrophy and Retinitis Pigmentosa." (PMID 36645183, 2023).
schizophrenia (7 papers, 2016 to 2023). A major psychotic disorder characterized by abnormalities in the perception or expression of reality. "Polymorphisms in PCDH15 gene have been found in association with schizophrenia and clinically significant copy number variations (CNVs) in PCDH15 locus have been identified as risk factor for bipolar disorder, ASD, and schizophrenia." (PMID 33352832, 2020). "Additionally, Pcdh15 gene variations, such as copy number variations and single nucleotide polymorphisms, have been implicated in neurodevelopmental disorders such as autism, bipolar disorder, and schizophrenia." (PMID 37595869, 2023). "Moreover, rare heterozygous SNVs in PCDH15 were detected in a patient with schizophrenia and ASD." (PMID 34948243, 2021).
bipolar disorder (6 papers, 2019 to 2025). A disorder of the brain that causes unusual shifts in mood, energy, activity levels and the ability to carry out day-to-day tasks. "Recent extensive genomic studies have implicated the protocadherin-related 15 (PCDH15) gene in the onset of psychiatric disorders, such as bipolar disorder (BD)." (PMID 38806495, 2024).
retinal degeneration (6 papers, 2008 to 2025). Degeneration of the retina. "It is notable that mutations in human PCDH21 are associated with cone-rod dystrophy and retinal degeneration, but an association of PCDH15 or other USH1 proteins with cone-rod dystrophy is, however, unclear." (PMID 34668518, 2021). "Defects in several of these ciliary DEGs have been associated with USH (Cep250 (atypical USH), Pcdh15 (USH1F) or other retinal ciliopathies Fam164a (RP28) leading to retinal degenerations as seen in USH2C patients with pathogenic variants in the ADGRV1 gene." (PMID 40103630, 2025). "Mouse models of the USH1 genes (Myo7a, shaker 1; Ush1c, deaf circler; Cdh23, waltzer; Pcdh15, Ames waltzer; Sans, Jackson shaker) exhibit circling behavior, head tossing and profound sensorineural hearing loss, but do not exhibit retinal degeneration." (PMID 19057657, 2008). "Should this explanation prove to be correct for the absence of retinal degeneration in v and av mutant mice, then increasing the levels of particular isoforms of CDH23 and PCDH15 in the mutant human retina might delay the onset or perhaps retard the progress of the RP component of USH1." (PMID 19057657, 2008).
Blindness (5 papers, 2018 to 2024). Blindness is the condition of lacking visual perception defined as a profound reduction in visual perception. "Thus, we present the first genetic animal model of a PCDH15-associated retinopathy that can be used to understand the aetiology of blindness in USH1." (PMID 34668518, 2021). "Mini-PCDH15 may also be a viable therapeutic option for addressing blindness." (PMID 37100771, 2023).
breast carcinoma (5 papers, 2015 to 2025). "Previously, the SNPs of the PCDH15 gene are known for associations with adverse events caused by chemotherapy in breast cancer as well as with lipid abnormalities." (PMID 25867717, 2015). "Another seven genes (CDH13, CDH7, CTNNA2, ERBB4, GRIK1, PCDH15, and TCF7L2) were reported as associated with the breast cancer by recent GWA studies." (PMID 28615668, 2017). "To elucidate the intricate roles of ADK fusion genes in HR+/HER2‒ breast cancer, we identified several distinct fusion events involving ADK with 6 different partner genes: PCDH15, SEC24C, KAT6B, RSU1, NARS2, and LRMDA." (PMID 41213951, 2025).
glioma (5 papers, 2022 to 2025). A benign or malignant brain and spinal cord tumor that arises from glial cells (astrocytes, oligodendrocytes, ependymal cells). "Gliomas with a low level of PCDH15 expression are associated with poorer patient survival outcomes, and xenografted grade IV glioblastoma multiforme cells produce nodular rather than diffuse tumours when they express low levels of PCDH1527." (PMID 35637313, 2022). "In the differential analysis, PCDH15 was found to be uniquely overexpressed in low-grade glioma, and previous studies have demonstrated that its aberrant expression profoundly affects patient prognosis." (PMID 41300698, 2025). "ALDOC was however expressed in a sporadic and infrequent pattern; very few cells in the EM gliomas expressed PCDH15 and VCAN." (PMID 37055795, 2023). "RNAscope analysis in 6 PM and 4 EM samples confirmed that the vast majority of cells in PM gliomas co-expressed PCDH15 and VCAN." (PMID 37055795, 2023). "Little is known about the function of Pcdh15 in the central nervous system (CNS), however, Pcdh15 expression can predict glioma aggression and promote the separation of embryonic human OPCs immediately following a cell division." (PMID 35637313, 2022). "Indeed, the overexpression of PCDH15 in glioma cell lines is sufficient to reduce proliferation and tumour growth following xenograft transplantation." (PMID 35637313, 2022). "However, reduced expression of PCDH15 has been shown to enhance oligodendrocyte progenitor cell proliferation and progression of gliomas." (PMID 36233050, 2022). "Low PCDH15 expression is driven by the overexpression of miR-22-5p, generated from the long non-coding RNA, MIR22HG, and overexpressing Pcdh15 in glioma cells can reduce xenograft growth and improve mouse survival." (PMID 35637313, 2022). "Our data indicate that Pcdh15 is a critical regulator of OPC proliferation and process motility, behaviours that characterise the function of these cells in the healthy CNS, and provide mechanistic insight into the role that Pcdh15 might play in glioma progression." (PMID 35637313, 2022).
autism spectrum disorder (4 papers, 2016 to 2024). A spectrum of developmental disorders that includes autism, and Asperger syndrome. "Our cross-disorder analysis of genic and regulatory CNVs in BD, SCZ, and autism spectrum disorder (ASD) identified PCDH15 variants in five, one, and two patients, respectively, establishing a link between PCDH15 deletion and BD pathogenesis." (PMID 38806495, 2024).
nonsyndromic deafness (4 papers, 2018 to 2025). An auditory system disease that is associated with permanent hearing loss caused by damage to structures in the inner ear and/or the middle ear, which is not associated with other signs and symptoms. "Similarly, mutations in PCDH15 have also been confirmed to be associated with USH1F and non-syndromic deafness DFNB23." (PMID 41049429, 2025).
autosomal recessive deafness (3 papers, 2021 to 2025). "However, mutations in PCDH15 have so far been associated with Usher I and nonsyndromic recessive hearing loss (DFNB23), but not yet with nonsyndromic vision loss." (PMID 33737949, 2021).
myopia (3 papers, 2018 to 2024). "In addition to the novel mutations found in five known myopia genes (ADAMTS18, CSMD1, P3H2, RPGR, and SLC39A5), we also identified pathogenic variants in seven ocular disease genes (ABCA4, CEP290, HSPG2, PCDH15, SAG, SEMA4A, and USH2A) as novel candidate genes." (PMID 30245926, 2018).
cone-rod dystrophy (2 papers, 2021 to 2023). Inherited retinal dystrophies that belong to the group of pigmentary retinopathies. "To date, no cases associated with PCDH15 mutations have been described as a cone-rod dystrophy." (PMID 34668518, 2021).
extrapulmonary tuberculosis (2 papers, 2011 to 2012). A tuberculosis that occurs at body sites other than the lung. "Recent reports elsewhere identified that single nucleotide polymorphisms rs4893980 on gene PDE11A of chromosome number 2, rs10488286 on gene KCND2 of chromosome number 7 and rs2026414 on gene PCDH15 of chromosome number 10 in humans were associated with extrapulmonary tuberculosis." (PMID 22770435, 2012).
glioblastoma (2 papers, 2021 to 2022). The most malignant astrocytic tumor (WHO grade IV). "Consistent with our results, miR-22 activated WNT signaling in glioblastoma by targeting Wnt inhibitor SFRP2 and PCDH15." (PMID 34345013, 2021).
Intellectual disability (2 papers, 2021 to 2023). "PCDH15 is closely related to electroencephalogram abnormalities in neuropsychiatric diseases, intellectual disability, and the development of schizophrenia." (PMID 37884635, 2023).
retinal disease (2 papers, 2025). "In addition, R-loops were identified in 20 genes involved in retinal disease including Ush2a, Pcdh15, and Abcc6." (PMID 39345562, 2025).
retinal dystrophies (2 papers, 2022). "Ten families had variants in genes related to a syndromic disease with retinal dystrophy (COL9A1, CEP290, PCDH15, LRP5, PEX1, CFH, COL2A1 and COL11A1)." (PMID 35457050, 2022). "Some of these proteins are well-studied in retinal dystrophy, such as CRB1, RP2, RPE65, and PCDH15." (PMID 36139394, 2022).
Anxiety (1 paper, 2024). Intense feelings of nervousness, tension, or panic often arise in response to interpersonal stresses. "Notably, Pcdh15-null brains at both ZT7 and ZT13 were characterized by decreased c-Fos levels in the amygdala, a pivotal region for emotions such as fear and anxiety." (PMID 38806495, 2024).
cardiomyopathy (1 paper, 2020). A disease of the heart muscle or myocardium proper. "For example, mutational combination of PCDH15 and USH1G have been identified in non‐syndromic hearing loss; oligogenic inheritance of three cardiomyopathy‐associated genes has been reported in a family with cardiac anomaly and supported by experimental evidence." (PMID 32815649, 2020).
cervical cancer (1 paper, 2013). A primary or metastatic malignant neoplasm involving the cervix. "Among the 49 PRC2 targets (defined by consistent hyper-MVPs) identified here were 10 genes of the cadherin superfamily in HPV+ HNSCC, including CDH8 and CDH13 (both also hypermethylated in cervical cancer, CDH18, CDH19, CDH23, PCDH10, PCDH15, PCDHB1, PCDHB4, and PCDHB15." (PMID 23419152, 2013).
coronary artery disease (1 paper, 2017). "PCDH15 gene can be involved in the susceptibility to coronary artery disease via alteration of lipid metabolism." (PMID 28120895, 2017).
COVID-19 (1 paper, 2023). A disease caused by infection with severe acute respiratory syndrome coronavirus 2. "We developed a PRS model for severe COVID-19, which showed that variants detected in ZNF568, GPR173, PCDH15, and IGSF3 were associated with severe COVID-19." (PMID 37547597, 2023).
epilepsy (1 paper, 2021). A brain disorder characterized by episodes of abnormally increased neuronal discharge resulting in transient episodes of sensory or motor neurological dysfunction, or psychic dysfunction. "Patient II, a girl (14 years of age) diagnosed with ID and affected by epilepsy, carried a frameshift de novo variant c.5573_5576 (p.(Lys1859Asnfs * 2)) of PCDH15 and a de novo splicing variant c.1074–11G > A of OPN4." (PMID 34948243, 2021). "We found a PCDH15 frameshift variant in a patient with ID, epilepsy, and language, and psychomotor delay and we hypothesized that, in part, it might contribute to the phenotype." (PMID 34948243, 2021).
hyperlipidemia (1 paper, 2024). "Pcdh15 was upregulated and has been associated with lipid levels in familiar hyperlipidemia." (PMID 39273278, 2024).
Infertility (1 paper, 2024). "We found evidence at non-hormonal, pleiotropic, infertility loci for recent directional selection (EBAG9) and balancing selection (GREB1, INHBB, PCDH15)." (PMID 38562841, 2024).
lipoma (1 paper, 2019). A benign, usually painless, well-circumscribed lipomatous tumor composed of adipose tissue. "In mice, lipoma HMGIC fusion partner-like 5 (LHFPL5) acts as an auxiliary subunit of the MET channel whose primary role is to correctly localize PCDH15 and TMC1 to the mechanotransduction complex." (PMID 32009898, 2019).
metabolic syndrome (1 paper, 2014). A cluster of metabolic risk factors for CARDIOVASCULAR DISEASES and TYPE 2 DIABETES MELLITUS. "Although the term photoreceptor outer segment has no biological relevance to CRP or inflammation, the genes enriched in this pathway have biological relevance to CRP (HNF1A), high triglycerides (PCDH15) and metabolic syndrome (GNAT3)." (PMID 24763700, 2014).
mood disorder (1 paper, 2020). A cognitive disorder a disturbance in which the person's mood is hypothesized to be the main underlying feature. "Changes in PCDH17 and PCDH15 have been implicated in mood disorder onset." (PMID 33352832, 2020).